Y_RNA (Y RNA )
Gene: Miscellaneous RNA gene on chromosome 14 (77,821,030 to 77,821,142, reverse strand). Ensembl gene ENSG00000199440.
Homologues: Orthologues: chimpanzee Y_RNA (100% identical). Paralogues in human: Y_RNA (91% identical), RNY1 (90% identical), Y_RNA (88% identical), RNY1P11 (88% identical), Y_RNA (87% identical), Y_RNA (86% identical), RNY1P10 (85% identical), Y_RNA (85% identical), RNY1P8 (84% identical), Y_RNA (84% identical), RNY1P12 (83% identical), RNY1P7 (83% identical), and 98 more.